MIR3118-2 (microRNA 3118-2)
Synonyms: hsa-mir-3118-2
Gene: MicroRNA gene on chromosome 15 (20,832,795 to 20,832,869, forward strand). Ensembl gene ENSG00000265322.
Homologues: Paralogues in human: MIR3118-3 (100% identical), MIR3118-4 (100% identical).